SDSL (serine dehydratase like)
Description:
Catalyzes the pyridoxal-phosphate-dependent dehydrative deamination of L-threonine and L-serine to ammonia and alpha-ketobutyrate and pyruvate, respectively. Also exhibits racemase activity towards L-glutamate and D-glutamate (By similarity).
Synonyms: cSDH; SDHL; SDH 2; SDS-RS1
Tractability: Small molecule: it has a high-quality binding pocket. PROTAC: ubiquitination databases record sites on it; its protein half-life has been measured.
Gene: Protein-coding gene on chromosome 12 (113,418,087 to 113,438,386, forward strand). Ensembl gene ENSG00000139410.
Subcellular location (Human Protein Atlas): Cytosol
Pathways (Reactome):
Metabolism: Serine metabolism; Threonine catabolism
Gene Ontology:
Molecular function: identical protein binding; L-serine ammonia-lyase activity; threonine deaminase activity; glutamate racemase activity; pyridoxal phosphate binding
Biological process: L-serine catabolic process; L-threonine catabolic process; amino acid metabolic process
Cellular component: cytosol
Genetic constraint (gnomAD): Loss-of-function variants: 27 observed, 29.82 expected, observed/expected ratio (o/e) 0.91, 90% interval 0.67 to 1.25. The upper end of that interval is the gene's LOEUF score, 1.25, which puts it in group 5 of 6, group 1 being the genes least tolerant of losing a copy. Missense variants: 431 observed, 435.2 expected, observed/expected ratio (o/e) 0.99, 90% interval 0.91 to 1.07. Synonymous variants: 196 observed, 185.91 expected, observed/expected ratio (o/e) 1.05, 90% interval 0.94 to 1.19.
Homologues: Orthologues: chimpanzee SDSL (99% identical), macaque SDSL (96% identical), pig SDSL (82% identical), rat Sdsl (81% identical), mouse Sdsl (81% identical), guinea pig SDSL (79% identical), rabbit SDSL (77% identical), tropical clawed frog sdsl (59% identical), dog SDSL (58% identical), zebrafish sdsl (55% identical), Caenorhabditis elegans cysl-1 (20% identical), Caenorhabditis elegans F01D4.8 (20% identical), and 5 more. Paralogues in human: SDS (60% identical), CBS (24% identical), SRR (22% identical), THNSL2 (17% identical), THNSL1 (15% identical).
Diseases named in the same sentence as SDSL in open-access papers:
SDSL is named in the same sentence as 9 diseases in open-access papers, as found by Europe PMC text mining. Sharing a sentence is not in itself a finding about the gene and the disease. The quoted sentences say what the papers report.
fungal infections (1 paper, 2017). "However, no information is available which link the human host immune response and the expression of SDSL during fungal infections." (PMID 28797245, 2017).
heart failure (1 paper, 2023). Inability of the heart to pump blood at an adequate rate to meet tissue metabolic requirements. "Western blot experiments, RT-PCR, and ISO-induced experiments confirmed that SDSL was highly expressed in heart failure patients and promoted heart failure progression." (PMID 38250028, 2023). "In this study, we discovered that SDSL was upregulated in heart failure via machine learning techniques, High expression of SDSL promotes the development of heart failure." (PMID 38250028, 2023). "As a result, we discovered that SDSL could promote the progression of heart failure, which provides a new therapeutic direction for heart failure treatment." (PMID 38250028, 2023). "However, there are only a few reports on the role of serine dehydratase-like (SDSL) in tumors and heart failure." (PMID 38250028, 2023). "Thus, it appears that SDSL acts as a factor that can promote myocardial cell apoptosis and contribute to the development of heart failure." (PMID 38250028, 2023). "To investigate whether SDSL is a biomarker for heart failure, we downregulated its expression and observed a decrease in the expression of Cleaved-PRAP1." (PMID 38250028, 2023). "However, compared to the ISO group, the promotion of myocardial cell apoptosis decreased, which suggests that SDSL may be a targeted biomarker for heart failure, as it can regulate PRAP1 and inhibit ISO-induced myocardial cell apoptosis." (PMID 38250028, 2023). "The analysis revealed that heart failure samples had significantly higher expression levels of EGFL7, SDSL, PPP1R13l, SMTNL2, MFAP4, and TAGLN genes, which may promote the development of heart failure." (PMID 38250028, 2023).
Insulin resistance (1 paper, 2019). Increased resistance towards insulin, that is, diminished effectiveness of insulin in reducing blood glucose levels. "Serine hydroxymethyltransferase 1 (SHMT1), ALDOC, SDSL, ASS1, and IDH3A are novel biomarkers for the development of insulin resistance." (PMID 30678306, 2019).
SDSL also shares sentences with these, for which no sentence is quoted: Alzheimer disease (1 paper); Cerebral atrophy (1); Pneumocephalus (1); Stroke (1); tuberculosis (1); tumours (1).